COPB1 (coat protein complex I subunit beta 1)
Description:
The coatomer is a cytosolic protein complex that binds to dilysine motifs and reversibly associates with Golgi non-clathrin-coated vesicles, which further mediate biosynthetic protein transport from the ER, via the Golgi up to the trans Golgi network. Coatomer complex is required for budding from Golgi membranes, and is essential for the retrograde Golgi-to-ER transport of dilysine-tagged proteins. In mammals, the coatomer can only be recruited by membranes associated to ADP-ribosylation factors (ARFs), which are small GTP-binding proteins; the complex also influences the Golgi structural integrity, as well as the processing, activity, and endocytic recycling of LDL receptors. Plays a functional role in facilitating the transport of kappa-type opioid receptor mRNAs into axons and enhances translation of these proteins. Required for limiting lipid storage in lipid droplets. Involved in lipid homeostasis by regulating the presence of perilipin family members PLIN2 and PLIN3 at the lipid droplet surface and promoting the association of adipocyte surface triglyceride lipase (PNPLA2) with the lipid droplet to mediate lipolysis (By similarity). Involved in the Golgi disassembly and reassembly processes during cell cycle. Involved in autophagy by playing a role in early endosome function. Plays a role in organellar compartmentalization of secretory compartments including endoplasmic reticulum (ER)-Golgi intermediate compartment (ERGIC), Golgi, trans-Golgi network (TGN) and recycling endosomes, and in biosynthetic transport of CAV1. Promotes degradation of Nef cellular targets CD4 and MHC class I antigens by facilitating their trafficking to degradative compartments.
Synonyms: COPB; BARMACS
Tractability: Antibody: UniProt places it where antibodies can reach, with high confidence; its Gene Ontology location is reachable by antibodies, with high confidence. PROTAC: ubiquitination databases record sites on it; its protein half-life has been measured.
Gene: Protein-coding gene on chromosome 11 (14,443,357 to 14,500,027, reverse strand). Ensembl gene ENSG00000129083.
Subcellular location: Cytoplasm; Golgi apparatus membrane; Cytoplasmic vesicle, COPI-coated vesicle membrane; Cell membrane; Endoplasmic reticulum-Golgi intermediate compartment
Subcellular location (Human Protein Atlas): Cytosol; Golgi apparatus; Vesicles
Pathways (Reactome):
Vesicle-mediated transport: COPI-dependent Golgi-to-ER retrograde traffic; COPI-mediated anterograde transport
Immune System: Neutrophil degranulation
Gene Ontology:
Molecular function: protein binding; structural molecule activity
Biological process: endoplasmic reticulum to Golgi vesicle-mediated transport; intra-Golgi vesicle-mediated transport; retrograde vesicle-mediated transport, Golgi to endoplasmic reticulum; intracellular protein transport; vesicle-mediated transport
Cellular component: cytosol; Golgi apparatus; Golgi membrane; membrane; plasma membrane; COPI vesicle coat; endoplasmic reticulum membrane; endoplasmic reticulum-Golgi intermediate compartment; ficolin-1-rich granule membrane; Golgi-associated vesicle; secretory granule membrane; tertiary granule membrane; transport vesicle; COPI-coated vesicle; COPI-coated vesicle membrane; cytoplasm; membrane coat
Genetic constraint (gnomAD): Loss-of-function variants: 13 observed, 76.74 expected, observed/expected ratio (o/e) 0.17, 90% interval 0.11 to 0.27. The upper end of that interval is the gene's LOEUF score, 0.27, which puts it in group 1 of 6, group 1 being the genes least tolerant of losing a copy. Missense variants: 757 observed, 977.03 expected, observed/expected ratio (o/e) 0.77, 90% interval 0.73 to 0.82. Synonymous variants: 318 observed, 336.08 expected, observed/expected ratio (o/e) 0.95, 90% interval 0.86 to 1.04.
Homologues: Orthologues: macaque COPB1 (99% identical), chimpanzee COPB1 (99% identical), mouse Copb1 (99% identical), rabbit COPB1 (99% identical), dog COPB1 (99% identical), pig COPB1 (99% identical), rat Copb1 (99% identical), guinea pig COPB1 (99% identical), tropical clawed frog copb1 (95% identical), zebrafish copb1 (94% identical), Drosophila melanogaster betaCOP (68% identical), Caenorhabditis elegans copb-1 (61% identical).
Diseases named in the same sentence as COPB1 in open-access papers:
COPB1 is named in the same sentence as 25 diseases in open-access papers, as found by Europe PMC text mining. Sharing a sentence is not in itself a finding about the gene and the disease. The quoted sentences say what the papers report.
breast carcinoma (4 papers, 2018 to 2023). "In breast cancer patients, a surge in gene expression linked to ER-Golgi transport processes is evident, exemplified by genes like ARF4, COPB1, and USO1." (PMID 37762375, 2023). "Together with the upregulation of COPB1 and USO1, which encode for the COPI subunit β1 and General vesicular transport factor p115, respectively and regulate ER-Golgi trafficking, ARF4 has been reported to be upregulated in breast cancer patient samples." (PMID 32426352, 2020). "A comprehensive meta-analysis of breast cancer cells also unravels that the expression patterns of ARF4, COPB1, and USO1 are orchestrated by the CREB3-like transcription factors." (PMID 37762375, 2023). "The discoveries highlight the pivotal roles that ARF4, COPB1, and USO1 undertake in breast cancer cell proliferation and invasiveness." (PMID 37762375, 2023). "This establishes a role for ARF4, COPB1, and USO1 in the regulation of breast cancer cell growth and invasion through the retrograde transport of proteins from the Golgi to ER via COPI-coated vesicles." (PMID 32426352, 2020).
cataract (2 papers, 2021 to 2026). Partial or complete opacity of the crystalline lens of one or both eyes that decreases visual acuity and eventually results in blindness. "Whole exome or genome sequencing of two families with a neuro-developmental syndrome, variable microcephaly and cataracts revealed biallelic variants in COPB1, which encodes the beta-subunit of COPI (β-COP)." (PMID 33632302, 2021).
microcephaly (2 papers, 2021 to 2025). A congenital or acquired developmental disorder in which the circumference of the head is smaller than normal for the person's age and sex. "Interfering RNA screens indicate that COPB1 may play an important role in cell division which could be linked to the microcephaly seen in these patients." (PMID 33632302, 2021). "RNA interference experiments showed that COPB1 plays a critical role in cell division, thus providing a mechanistic link to the microcephaly phenotype in COPB1 patients." (PMID 40552310, 2025). "Mutations in COPB1 that result in the altered interaction between β-COPI and β′-COPI were found in patients suffering from severe cataracts, developmental delay, and microcephaly, a clinical manifestation often associated with a change in the mode of division of neural stem cells." (PMID 40552310, 2025).
osteoporosis (2 papers, 2022 to 2025). A condition of reduced bone mass, with decreased cortical thickness and a decrease in the number and size of the trabeculae of cancellous bone (but normal chemical composition), resulting in increased fracture incidence. "Finally, we screened four candidate proteins of osteoporosis with iron accumulation, GSTP1, LAMP2, COPB1, and RAB5B." (PMID 36313751, 2022). "Together, these 4 core proteins (GSTP1, LAMP2, COPB1, and RAB5B) may account for osteoporosis with iron accumulation, and potentially be a serum marker for it." (PMID 36313751, 2022). "We ultimately identified 4 core proteins (GSTP1, LAMP2, COPB1, RAB5B) that were significantly differentially expressed in the bone of osteoporosis patients with iron accumulation, and validated the changed protein level in the serum of the medical examination population." (PMID 36313751, 2022). "Therefore, we speculate that these 4 DEPs (GSTP1, LAMP2, COPB1, RAB5B) may be novel candidate core proteins of osteoporosis with iron accumulation." (PMID 36313751, 2022).
bladder cancer (1 paper, 2025). "First, we performed Co‐IP assay to confirm endogenous binding of COPA, COPB2, COPB1, and COPG in bladder cancer cells." (PMID 40112217, 2025).
clear cell carcinoma of the kidney (1 paper, 2023). "As for COPB1, it is positively related with PD-L1 in a number of malignant tumors including clear cell carcinoma of the kidney, sarcoma, gastric cancer, thyroid carcinoma and thymoma." (PMID 37791813, 2023).
Immunodeficiency (1 paper, 2026). Failure of the immune system to protect the body adequately from infection, due to the absence or insufficiency of some component process or substance. "Although immunodeficiency has been observed in patients with COPB1 deficiency, the immunological phenotype remains incompletely characterized." (PMID 41676145, 2026).
lung carcinoma (1 paper, 2012). "In this cluster, NT5C2, API5, CPN, PRKAR1A and COPB1 were fully down-regulated in lung cancer." (PMID 23122428, 2012).
infection (12 papers, 2015 to 2025). The state of being infected such as from the introduction of a foreign agent such as serum, vaccine, antigenic substance or organism. "In contrast, a significant reduction in total RNA counts was detected at 10 h post-infection, further supporting that COPB1 is important for SARS-CoV-2 RNA synthesis." (PMID 40167317, 2025). "Of our identified host factors, 54 significantly alter IAV infection upon siRNA knockdown, and two factors, AHNAK and coatomer subunit COPB1, are also essential for productive infection by SARS-CoV-2." (PMID 37758692, 2023). "For the three cellular genes with the greatest impact on rHAZV-eGFP expression, namely, COPI coat-like complex components COPA and COPB2 and the adapter-like component COPB1, further validation of their observed impact was performed using infections WT rHAZV." (PMID 32581103, 2020). "Three of these IAV host factors also regulate infection by SARS-CoV-2, acting as pro-viral (COPB1, AHNAK) or antiviral (RUVBL2) factors of SARS-CoV-2 infection." (PMID 37758692, 2023). "COPB1 was shown to be essential for Influenza A Virus (IAV) infection in siRNA-based study and it was also required for the infection of RNA viruses including vesicular stomatitis virus and SARS-CoV-2, for facilitating essential steps in viral RNA synthesis and trafficking or viral assembly." (PMID 40115189, 2025). "First, confirmation of the knockdown of the corresponding genes was achieved using quantitative reverse transcriptase PCR (qRT-PCR) targeting COPA, COPB1, and COPB2, for which mRNA copy numbers in knockdown cells were reduced in all three cases by ≥50% compared to the untreated infection controls." (PMID 32581103, 2020).
cancer (3 papers, 2012 to 2026). A tumor composed of atypical neoplastic, often pleomorphic cells that invade other tissues. "Expression analyses revealed broad upregulation of coatomer genes across cancer types, with COPG1 and COPB1 emerging as strong risk-associated genes (HR > 2)." (PMID 41751842, 2026). "COPB1 and COPB2, components of the COPI complex, were considered as attractive candidates for further study based on the significant impact in cancer cells on both cell viability and autophagosome formation." (PMID 22745748, 2012). "Reduced expression of COPA, COPB1, COPB2, COPG1, COPD, and COPZ1 induced the punctate GFP-LC3 formation in MDA-MB-231, MDA-MB-468 and SKOV3 cancer cell lines." (PMID 22745748, 2012).
tumor (2 papers, 2012 to 2020). "In all cell lines tested, we observed that depletion of the coatomer protein complex subunit beta 1 (COPB1) caused an accumulation of the LC3-positive speckles that are suggestive of autophagy, indicating that the autophagy mechanism is conserved among different tumor lineages." (PMID 22745748, 2012). "Similarly, only EVs released by hypoxic tumours were found to contain the ‘coatomer’ complex of subunits alpha (COPA), beta (COPB1), and epsilon (COPE), which mediate protein cargo transport between the Golgi and endoplasmic reticulum." (PMID 33050615, 2020).
COPB1 also shares sentences with these, for which no sentence is quoted: chlamydial infection (5 papers); developmental delay (1); gastric cancer (1); intellectual disability syndrome (1); keratitis (1); lymphopenia (1); mercury (1); mesothelioma (1); neutropenia (1); prostate carcinoma (1); sarcoma (1); thymoma (1); thyroid carcinoma (1); viral infection (1).